MARVELD1 (MARVEL domain containing 1)
Diseases named in the same sentence as MARVELD1 in open-access papers (continued):
Sharing a sentence is not in itself a finding about the gene and the disease.
lung adenocarcinoma (2 papers, 2014 to 2022). A carcinoma that arises from the lung and is characterized by the presence of malignant glandular epithelial cells. "The plasmid was transfected into immortal human bronchial epithelial cells 16HBE that expressed high level of MARVELD1 and human lung adenocarcinoma epithelial cells A549." (PMID 25520033, 2014).
ovarian carcinoma (2 papers, 2022 to 2023). A malignant neoplasm originating from the surface ovarian epithelium. "Low expression of MARVELD1 was also related to ovarian cancer platinum- and taxane-based chemotherapy resistance." (PMID 34976185, 2022).
adenosquamous carcinoma (1 paper, 2014). A carcinoma composed of malignant glandular cells and malignant squamous cells. "MARVELD1 expression was also dramatically reduced, either negative (−) or weak (+) expression, 91.4% in adenocarcinoma tissues, 97.7% in squamous cell carcinoma, 90% in adenosquamous carcinoma, 65% in bronchioalveolar cell carcinoma, and 60% in large cell lung carcinoma." (PMID 25520033, 2014).
bladder cancer (1 paper, 2019). "MARVELD1 was found to be downregulated in several cancer types including bladder cancer." (PMID 31212967, 2019).
cognitive disorder (1 paper, 2018). A disease affects cognitive processes. "The cognitive disorder was found in 6–8-week-old MARVELD1 KO mice as well." (PMID 30250269, 2018).
pancreatic cancer (1 paper, 2022). "Low expression of MARVELD1 in pancreatic cancer was associated with poor OS unlike in cancers with high expression levels of MARVELD1 in our cohort." (PMID 34976185, 2022).
small cell lung carcinoma (1 paper, 2014). Small cell lung cancer (SCLC) is a highly aggressive malignant neoplasm, accounting for 10-15% of lung cancer cases, characterized byrapid growth, and early metastasis. "MARVELD1 expression in all the tested tumor adjacent control cases were positive (++ or +++); However, its expression in small cell lung cancer tissues was negative (94.5%; 52/55) or very weak (5.5%; 3/55)." (PMID 25520033, 2014).
tumor (11 papers, 2013 to 2025). "Meanwhile, the high expression of MARVELD1 in tumor tissues was closely associated with a poor prognosis in cancer patients." (PMID 36750717, 2023). "Overall, our results underline the link between MARVELD1 and PARP1 in therapeutic resistance based on DDR and provide new insights for clinical tumor therapy of PARPi." (PMID 36750717, 2023). "Collectively, our findings indicate that DNA methylation and histone modification synergistically affect the expression of MARVELD1, which inhibited tumor occurrence and progression via Wnt/β-catenin signaling." (PMID 34976185, 2022). "Expression of MARVELD1 in tumor and non-tumor tissues, the relationship between its expression and cancer prognosis, and upstream regulation of MARVELD1 were examined using pan-cancer data from The Cancer Genome Atlas." (PMID 34976185, 2022). "Further studies are required to elucidate the upstream regulation and biological functions of MARVELD1 in tumor progression." (PMID 34976185, 2022). "Overall, MARVELD1—a tumor suppressor that is epigenetically modified—inhibits the occurrence and progression of tumors through the Wnt/β-catenin signaling pathway." (PMID 34976185, 2022). "MARVELD1 is located on human chromosome 10q24, which functions in the proliferation and migration of tumor cells and participates in the malignant progression of various cancers." (PMID 34008750, 2021). "Previous studies showed that MARVELD1 expression is lower in tumour cells, and MARVELD1 regulates the balance of ITGB1 and ITGB4 expression in cancer cells." (PMID 30250269, 2018). "Initially, MARVELD1 was recognized for its role in cell proliferation and cell migration in tumour cells." (PMID 30250269, 2018). "Kaplan-Meier survival analysis showed that negative MARVELD1 expression correlated with reduced patient survival compared with positive MARVELD1 expression in tumor tissues (P = 0.018; Hazard Ratio (HR) = 0.314; 95% Confidence Interval (CI), 0.12–0.82)." (PMID 25520033, 2014). "We found 63.6% (21 out of 33 NSCLC) in grade I tumor showed the reduced MARVELD1 expression, but 96.9% (62 out of 64) in the advanced grades (grade II to III) (P < 0.001)." (PMID 25520033, 2014). "We previously reported that MARVELD1 localized to interphase cell nuclei and was downregulated in multiple tumor tissues." (PMID 23826386, 2013). "Furthermore, using CRC PDX models, we assessed the tumor suppressive effect of the combination of 5-FU and olaparib to explicate the partnership of MARVELD1 and PARP1." (PMID 36750717, 2023). "Furthermore, MARVELD1 negatively regulates many tumor-related signaling pathways in COAD, including canonical Wnt, TGF-beta receptor, JAK-STAT cascade, BMP, Rap1, Ras, Hippo, MAPK, and PI3K-Akt signaling pathways." (PMID 34976185, 2022). "Moreover, the median tumor weight in the MARVELD1 overexpression group was lower than that in the control group (all P < 0.05)." (PMID 34976185, 2022). "Therefore, when BALB/c mice were injected with HCT116-controls or HCT116-flag-MARVELD1, the overexpression of MARVELD1 inhibited tumor growth compared with the controls." (PMID 34976185, 2022). "MARVELD1 is a potential tumor suppressor, which negatively regulates proliferation of cancer cells." (PMID 25520033, 2014). "Therefore, our findings also suggest that MARVELD1 may be a tumor therapeutic intervention protein that acts as a positive guardian of genomic stability through mediating the DDR process." (PMID 36750717, 2023). "Therefore, we hypothesized that MARVELD1, a tumor suppressor, is biphasically regulated via DNA methylation and histone modification, resulting in its reduced expression in cancer tissues." (PMID 34976185, 2022). "Likely due to the greater sequencing read depth, patient 1,010,020 had a substantially greater number of such genes—a total of 187; these likewise included several tumor suppressor genes, such as ANGPTL4, ARHGEF10, MARVELD1, and SQSTM1." (PMID 41428220, 2025).
tumor (continued). "We found that MARVELD1 was highly expressed in adjacent noncancerous lung tissues compared with tumor tissues." (PMID 25520033, 2014). "We have observed low expression levels of MARVELD1, a novel tumor repressor, in multiple tumors; however, its function in normal cells has not been explored." (PMID 23826386, 2013).
cancer (10 papers, 2014 to 2023). A tumor composed of atypical neoplastic, often pleomorphic cells that invade other tissues. "Low expression of MARVELD1 was associated with poor disease outcomes in pan-cancer." (PMID 34976185, 2022). "These evidences demonstrate that MARVELD1 is clearly involved in tumorigenesis and resistance to cancer therapy by participating in DDR." (PMID 36750717, 2023). "In particular, authors observed hypermethylation of the MARVEL domain containing 1 (MARVELD1) locus that affected its expression levels in various cancers, including TMs." (PMID 36672310, 2023). "Second, we analyzed the regulation upstream through epigenetic modification, and the transcription factors of MARVELD1 from pan-cancer data obtained from TCGA." (PMID 34976185, 2022). "In most types of cancer, every methylation site in the MARVELD1 promoter locus was significantly hypermethylated than in their non-cancer counterparts." (PMID 34976185, 2022). "As expected, significant hypermethylation of the 13 MARVELD1 methylation sites was observed in the tissues from the pan-cancer data compared to the non-cancer tissues from TCGA." (PMID 34976185, 2022). "Data from 19,639 patients representing 33 cancer types obtained from TCGA were also examined to analyze the relationship between the methylation status of MARVELD1 promoter locus and its corresponding expression." (PMID 34976185, 2022). "Analyzing TCGA and 450K array databases, we predicted 13 methylation sites in the MARVELD1 promoter locus, which were hypermethylated in tissues from the pan-cancer data compared with those in non-cancer tissues." (PMID 34976185, 2022). "In this study, we showed that the expression of MARVELD1 was downregulated in pan-cancer, which is consistent with previous reports." (PMID 34976185, 2022). "Hypermethylation and histone modification in the MARVELD1 promoter locus synergistically affected its expression in pan-cancer." (PMID 34976185, 2022). "The results indicated that MARVELD1 expression was inversely proportional to the DNA methylation level found in the pan-cancer data." (PMID 34976185, 2022). "The results indicated that H3K27ac and H3K4me3 were enriched in the MARVELD1 promoter locus in ten cancer cell lines representing 10 cancer types, namely U87, MCF-7, LoVo, LNCaP, IMR90, HCT116, HCC1954, H128, Caco-2, and A549." (PMID 34976185, 2022). "In this study, first, we clarified the relationship between MARVELD1 expression and prognosis in pan-cancer from TCGA." (PMID 34976185, 2022). "In this study, we used TCGA pan-cancer database to further analyze the correlation between the expression of MARVELD1 and epigenetic modifications." (PMID 34976185, 2022). "Every methylation site in the MARVELD1 promoter locus was significantly hypermethylated than in its non-cancer counterpart in most types of cancers." (PMID 34976185, 2022). "Data from 10,534 patients representing 33 cancer types were obtained from TCGA pan-cancer database and were used to validate the expression of MARVELD1." (PMID 34976185, 2022). "The expression of MARVELD1 was significantly downregulated in cancer tissues compared to that in normal tissues in pan-cancer." (PMID 34976185, 2022). "TCGA data was used to validate the association of low expression of MARVELD1 with poor DSS and PFI in pan-cancer." (PMID 34976185, 2022). "Kaplan-Meier analysis and the log-rank test were used to explore the relationship between MARVELD1 expression and survival status in patients using pan-cancer database samples." (PMID 34976185, 2022). "MARVELD1 expression was significantly downregulated in tissues used for pan-cancer analysis compared to that in normal tissues." (PMID 34976185, 2022). "It has been proven that MARVELD1 is lowly expressed in many cancers, such as cervical cancer, breast cancer, and prostate cancer." (PMID 34008750, 2021).
cancer (continued). "We previously demonstrated that novel identified nuclear factor MARVELD1 was widely expressed in human tissues, but down-regulated by promoter methylation in multiple cancers." (PMID 25520033, 2014). "This study was conducted to evaluate the 1) expression of MARVELD1 in human cancer tissues and adjacent normal tissues, 2) relationship between its expression and disease prognosis, and 3) upstream regulation of MARVELD1 using pan-cancer data from The Cancer Genome Atlas (TCGA)." (PMID 34976185, 2022). "In addition to DNA methylation, we also found that H3K27ac and H3K4me3 were enriched in the MARVELD1 promoter locus in ten cancer cell lines, including U87, MCF-7, LoVo, LNCaP, IMR90, HCT116, HCC1954, H128, Caco-2, and A549." (PMID 34976185, 2022). "Therefore, it is pertinent to study the epigenetic modifications that regulate MARVELD1 expression using pan-cancer data." (PMID 34976185, 2022). "TCGA data were downloaded and analyzed to assess the expression of MARVELD1 in human cancers." (PMID 34976185, 2022). "Interestingly, MARVELD1 is highly expressed in many different tissue types, downregulated in many cancers, and epigenetically silenced via DNA methylation, further demonstrating the similarities between cancer and PAS at the molecular level." (PMID 30057649, 2018). "MARVELD1 PARylation offers functional evidence of MARVELD1 involved in the DDR system, and the PARylation sites can serve as a potential target for cancer therapy in clinical trials." (PMID 36750717, 2023). "Previous studies showed that MARVELD1 mediated the balance between ITGB1 and ITGB4 in cancer cells through down-regulating the expression of ITGB1 in mRNA processing and up-regulating ITGB4 by binding its promoter." (PMID 30250269, 2018). "Our previous investigation found that MARVELD1 regulated the expression of ITGB1 and ITGB4 in cancer cells." (PMID 30250269, 2018). "These proteins are also involved in DNA replication licensing factors (3–7 subunits in six factors of MCM), the YWHA family (six members) and regulators of cell death besides oxidation reduction, suggesting that MARVELD1 mediates the DDR process and links with cancer therapy." (PMID 36750717, 2023). "This view may be somewhat controversial, as several reports indicate inhibition of NMD in cancer cells, due to inhibition of NMD regulators such as MARVELD1 and UPF1 through promoter hypermethylation." (PMID 34634811, 2021).
MARVELD1 also shares sentences with these, for which no sentence is quoted: adenocarcinoma (1 paper); breast carcinoma (1); colon adenocarcinoma (1); endocervical adenocarcinoma (1); head and neck squamous cell carcinoma (1); large cell lung carcinoma (1); male germ cell tumor (1); non-small cell lung carcinoma (1); pancreatic adenocarcinoma (1); paraganglioma (1); pheochromocytoma (1); prostate adenocarcinoma (1); sarcoma (1); skin cutaneous melanoma (1); squamous cell carcinoma (1); thymoma (1); thyroid carcinoma (1); uterine corpus endometrial carcinoma (1).